GPRC5C (G protein-coupled receptor class C group 5 member C)
Description:
This retinoic acid-inducible G protein-coupled receptor provide evidence for a possible interaction between retinoid and G-protein signaling pathways.
Synonyms: RAIG-3; RAIG3
Tractability: Antibody: its Gene Ontology location is reachable by antibodies, with high confidence; UniProt places it where antibodies can reach, with medium confidence; UniProt predicts a signal peptide or a membrane-spanning region; the Human Protein Atlas places it where antibodies can reach. PROTAC: ubiquitination databases record sites on it; its protein half-life has been measured.
Target class: Family C G protein-coupled receptor; Membrane receptor
Gene: Protein-coding gene on chromosome 17 (74,424,851 to 74,451,653, forward strand). Ensembl gene ENSG00000170412.
Subcellular location: Cell membrane; Cytoplasmic vesicle membrane
Subcellular location (Human Protein Atlas): Plasma membrane; Vesicles; Nucleoplasm; Primary cilium; Primary cilium transition zone
Gene Ontology:
Molecular function: protein binding; G protein-coupled receptor activity; protein kinase activator activity
Biological process: G protein-coupled receptor signaling pathway
Cellular component: extracellular exosome; plasma membrane; receptor complex; vesicle; cytoplasmic vesicle membrane; membrane
Genetic constraint (gnomAD): Loss-of-function variants: 22 observed, 28.31 expected, observed/expected ratio (o/e) 0.78, 90% interval 0.55 to 1.11. The upper end of that interval is the gene's LOEUF score, 1.11, which puts it in group 4 of 6, group 1 being the genes least tolerant of losing a copy. Missense variants: 547 observed, 592.45 expected, observed/expected ratio (o/e) 0.92, 90% interval 0.86 to 0.99. Synonymous variants: 246 observed, 260.77 expected, observed/expected ratio (o/e) 0.94, 90% interval 0.85 to 1.05.
Homologues: Orthologues: chimpanzee GPRC5C (99% identical), macaque GPRC5C (95% identical), dog GPRC5C (92% identical), pig GPRC5C (89% identical), rat Gprc5c (89% identical), mouse Gprc5c (88% identical), rabbit GPRC5C (88% identical), guinea pig GPRC5C (87% identical), tropical clawed frog gprc5cl1 (59% identical), zebrafish gprc5c (47% identical). Paralogues in human: GPRC5B (37% identical), GPRC5A (30% identical), GPRC5D (28% identical).
Diseases named in the same sentence as GPRC5C in open-access papers:
GPRC5C is named in the same sentence as 15 diseases in open-access papers, as found by Europe PMC text mining. Sharing a sentence is not in itself a finding about the gene and the disease. The quoted sentences say what the papers report.
neuroblastoma (3 papers, 2023 to 2025). Neuroblastoma (NB) is the most common solid, extracranial childhood tumor. "Interestingly, GPRC5C expression has also been associated with the maintenance of the neuroblastoma cancer stem cell population, being a distinctive marker of the highly tumorigenic I-type stem cells." (PMID 36674750, 2023). "GPRC5C is consistently elevated exclusively in neuroblastoma cancer stem cells." (PMID 38322112, 2024).
ciliopathy (1 paper, 2023). A genetic disorder of the cellular cilia or the cilia anchoring structures, the basal bodies, or of ciliary function. "Absence of Gprc5c does not cause typical ciliopathy-related phenotypes, but alters the ciliary transport of components involved in olfactory signal transduction and detection of olfactory cues." (PMID 38110903, 2023).
colorectal cancer (1 paper, 2018). A primary or metastatic malignant neoplasm that affects the colon or rectum. "Results using the ExoScreen assay from the same group showed that detection of CD145/CD9 dual positive cancer EVs is possible using 5 μL serum of colorectal cancer patients, and that EVs positive for GPRC5C/CD63 can discriminate pancreatitis patients from stage II pancreatic cancer." (PMID 31162490, 2018).
COVID-19 (1 paper, 2022). A disease caused by infection with severe acute respiratory syndrome coronavirus 2. "G Protein-Coupled Receptor Class C Group 5 Member C (GPRC5C) whose structural variants have been associated with poor prognosis in COVID-19." (PMID 36143338, 2022).
leukaemia (1 paper, 2023). "Moreover, an association between GPRC5C expression and alteration of the metabolic profile has recently been demonstrated for leukaemia cells." (PMID 38110903, 2023).
nematode infection (1 paper, 2021). "Taste receptor TAS2R16, adhesion receptor ADGRG6 (GPR126) and orphan receptor GPRC5C were enriched in abomasal tuft cells, and our data suggest these may be the main receptors involved in sensing nematode infection in the abomasum." (PMID 34880874, 2021).
cancer (9 papers, 2018 to 2024). A tumor composed of atypical neoplastic, often pleomorphic cells that invade other tissues. "The expression of FBP1 and TAPBPL was significantly high in BC tissues, and moderate expression of GPRC5C was found both in breast normal tissue and cancer tissue." (PMID 36358906, 2022). "Of these 32, several genes (mt-Nd3, mt-Nd4l) involved in mitochondrial metabolism have emerged, as well as other genes such as Epcam and Gprc5c involved in cancer stemness and dormancy of HSCs, respectively, and Cdcp1 that is expressed on leukemic blasts." (PMID 34550965, 2021). "Chemokine receptor signaling was of interest, and we found CXCR4 and CXCR5 comentioned with GPRC5C in a review of vascular development dysregulation relevant to cancer." (PMID 34007962, 2021). "High-risk prognostic genes BMP4, CELSR3, GPRC5C, and RUNDC3B, highly expressed in Epithelial Cells, CCBE1 showed expression in Leydig cells, SCGB2A2 highly expressed in Epithelial Cells and Cancer cells, suggesting that Epithelial cell play an important role in tumor growth and initiation." (PMID 37985782, 2023).
tumor (9 papers, 2014 to 2025). "CXCR4, nominated from literature comention with GPRC5C, has roles in immunity and a tumor microenvironment in addition to angiogenesis." (PMID 34007962, 2021).
infection (1 paper, 2014). The state of being infected such as from the introduction of a foreign agent such as serum, vaccine, antigenic substance or organism. "TJP2 was also positively regulated, while GPRC5C was negatively regulated 90 min post-infection." (PMID 25101063, 2014).
GPRC5C also shares sentences with these, for which no sentence is quoted: breast carcinoma (2 papers); acute myeloid leukemia (1); neurodegenerative disease (1); pancreatic cancer (1); pancreatitis (1); Parkinson disease (1).